MMP2 (matrix metallopeptidase 2)
Diseases named in the same sentence as MMP2 in open-access papers (continued):
Sharing a sentence is not in itself a finding about the gene and the disease.
tumor (continued). "In summary, we provide evidence from cells, xenograft tumors, and human tumors to demonstrate that an increase in Bcl-2 protein stability due to its phosphorylation at Serine 87 is responsible for tumor progression and metastasis via increased MMP2 expression." (PMID 25826088, 2015). "CEBPD expression enhances tumor invasiveness by directly binding to the MMP2 promoter, resulting in transcriptional upregulation." (PMID 26307680, 2015). "Matrix-degrading enzyme MMP2 can regulate tumor cell migration by digesting extracellular matrix surrounding tumor tissues." (PMID 26329521, 2015). "The high expression of MMP-2 by tumour cells translates to greater degradation of basement membrane (BM) and extracellular matrix (ECM), thus providing channels that allow tumour cells to migrate and metastasize by direct spread and in vascular systems." (PMID 26155333, 2015). "In this study, we found that only miR-29b inhibited tumor cell migration and invasion by reducing MMP-2 activity via phospho-AKT/β-catenin signaling, and stimulated a more epithelial-like morphology." (PMID 26155940, 2015). "MMP2 and MMP9 are over-expressed in the invadopodia at the leading edge of tumours, but also when MMP2 is expressed in the surrounding stroma or MMP9 at pre-metastatic sites they can exert pro-metastatic activity." (PMID 26513020, 2015). "What had to be declared was that as two articles provided information about MMP-2 expression in tumor cells and stroma cells, we processed each one independently as two studies in the meta-analysis." (PMID 25816052, 2015). "At least 20 types of MMPs have been identified to date, and MMP-2 and -9 are highly correlated with tumor invasiveness and metastatic potency." (PMID 25670016, 2015). "Hematoxylin and eosin staining and immunohistochemical staining for MMP2 and CD11b further confirmed the precision of tumour dissection." (PMID 26395067, 2015). "MMPs, including MMP-2, -9 and -14, which are overexpressed in tumor cells, aid migration and invasion by modifying the cellular microenvironment." (PMID 25394920, 2015). "Previous studies have shown that increased expression of matrix metalloproteinase-2 (MMP-2) and MMP-9 is associated with enhanced tumor invasion and metastasis." (PMID 26021863, 2015). "Selective P2X7 antagonist, oATP, inhibited tumor angiogenesis via suppression of MMP-2, MMP-9, and VEGF." (PMID 25933224, 2015). "The preferential uptake of cleavable ACPPD-Gd versus D-amino acid controls has been validated not only in other MMP-expressing tumor models, but also in acute stroke, where MMP-2/9 have also been shown to be overexpressed." (PMID 26336058, 2015). "FAK overexpression occurs early in HNSCC development, correlating with increased tumor cell invasion and lymph node metastasis, partially through an increase in MMP-2 and MMP-9 secretion." (PMID 25734659, 2015). "MMP-2 and MMP-9 cleave type IV collagen, the major structural protein for ECM and basement membrane and are consequently associated with tumor development." (PMID 25888629, 2015). "Previous studies have suggested that miR-29b exerts its tumor-suppressing function by targeting oncogenes such as Bcl-2, Mcl-1, and MMP-2." (PMID 26512921, 2015). "MMP-2 and -9 are the kind of gelatinase and collagenase demonstrated to be involved in migration and invasion of tumor cells." (PMID 26699938, 2015). "Hydration of the extracellular matrix is crucially important for cancer cell invasion and metastasis, a process that tumor cells promote through the secretion of proteins such as matrix metalloproteinase-2 (MMP-2) and MMP-9." (PMID 25402510, 2015). "IHC staining reaction of the tumor was present in 44-60 % for MMP2, MMP7, and MMP9, as well as in 96 % and 80 % for mTOR and p-mTOR, respectively." (PMID 26652716, 2015). "It has been well documented that CD147 induces the expression of several MMPs, such as MMP-1, MMP-2, MMP-9, which are associated with tumor migration and invasion." (PMID 26507719, 2015).
tumor (continued). "The consistent association between ATF3 and MMP2 expression suggests that ATF3 exerts a similar function with MMP2 in some ways, and plays a role in promoting tumor metastasis." (PMID 25872784, 2015). "Since the 72 kDa type IV collagenase (MMP2) degrades collagen IV, one of the major components of the basement membrane, it is thought to be of special significance during tumour invasion." (PMID 26135631, 2015). "Direct contact between fibroblasts and tumor cells upregulated the secretion and activation of MMP-2, but only NFs increased TIMP-1 production." (PMID 25885552, 2015). "Our previous studies have demonstrated that the level of plasma Hsp90α is positively correlated with the tumor malignancy in clinical cancer patients and the secreted Hsp90α stabilizes MMP-2 to facilitate tumor invasion." (PMID 25823663, 2015). "MMP-2 was significantly more strongly expressed in tumor cells on the positive margins than in the main tumor mass, with an average of 109.0237 (SD 64.0751; P = 0.0301)." (PMID 25097794, 2014). "MMP2 and MMP9 have been frequently detected to be over-expressed in solid tumors and associated with tumor invasion and metastasis." (PMID 25250801, 2014). "As is well known, MMP-2 and MMP-9 have been implicated in metastasis and invasion of malignant tumor cells." (PMID 25496480, 2014). "It has been previously shown for tumor cells that AMF-induced motility is mediated by upregulation of MMP2 and MMP3." (PMID 24736611, 2014). "We determined the serum levels and tumor tissue expression of MMP-2 and TIMP-2 in 72 CRC patients in relation to clinicopathological features of cancer as well as the prognostic significance of all variables tested for CRC patients’ survival." (PMID 24395652, 2014). "MMP-2 interacts with integrins and results in locally-enhanced matrix degradation and elevated MMP-2 and MMP-9 expression is associated with tumor aggressiveness and invasion." (PMID 24959847, 2014). "Transcripts for MMP-2 were more frequently expressed in mesenchymal tumor cells than in epithelial tumor cells." (PMID 24395652, 2014). "Dimerization in the CD147 crystal structure plays an important role in allowing CD147 to take part in tumor cell invasion and MMP-2 production." (PMID 25268615, 2014). "The cyclic peptide CTTHWGFTLC (CTT) containing a His-Trp-Gly-Phe motif has been described as a selective MMP-2 inhibitor that reduces the migration of both human endothelial and tumor cells, and prevents tumor growth and invasion in animal models." (PMID 25547485, 2014). "The percentage of MMP-2-positive cases decreased with tumor stage; it was the lowest in stage D as well in cancer cells as in interstitial inflammatory infiltrate cells." (PMID 24395652, 2014). "Matrix metalloproteinases (MMPs) are involved in the degradation of the basement membrane and epimatrix, among which MMP-2 and -9 markedly correlate with tumor invasion." (PMID 25120638, 2014). "Expression of oncoproteins related to tumor metastasis, such as MMP2, MMP9, and CD44, was also significantly reduced." (PMID 24387290, 2014). "In these tumors, well-known markers of tumor progression able to modulate tumor invasion and metastatic potential, such as Mmp2 and Mmp9, were consistently up-regulated." (PMID 24928374, 2014). "A number of ECM degrading MMPs, such as MMP1, MMP2 and MMP14, have been implicated in the process of tumor invasion and metastasis." (PMID 25349534, 2014). "Specifically, high expression of tumor-derived PDGF-BB and MMP-1 were associated with increased cancer survival (p < 0.05), while high expression of MMP-2 showed a trend towards improved outcome (p = 0.058)." (PMID 25483099, 2014). "This investigation intended to evaluate the association between FN-1, ITGA-3, ITGB-5, MMP-2, and MMP-9 gene and protein expression levels in tumor tissue with clinical and histopathological neoplastic parameters of cancer dissemination." (PMID 24737953, 2014).
tumor (continued). "Both in vitro and in vivo assays indicated that ablation of endogenous EIF5A2 inhibited tumor angiogenesis by reducing matrix metalloproteinase 2 (MMP-2) expression." (PMID 25071013, 2014). "MMP-2 and -9 play critical roles in tumor cell invasion and metastasis by degradation of type IV collagen, a major component of the ECM and basement membrane." (PMID 24190483, 2014). "The significant correlation between CK-positivity of BM and VEGF expression as well as MMP-2 activity in tumor was shown." (PMID 24669218, 2014). "From these results we conclude that AMF produced by HCC likely mediates the enhancement in MMP2 activity observed in MSCs when these cells are exposed to tumor conditioned medium." (PMID 24736611, 2014). "They demonstrated that miR-340 suppresses tumor migration and invasion by directly targeting c-Met and consequently MMP-2 and -9." (PMID 24670365, 2014). "In the hypoxia context, lysyl oxidase secreted by hypoxic tumor cells accumulates at pre-metastatic sites, resulting in CD11b + myeloid cell recruitment and increased production of MMP-2." (PMID 25303976, 2014). "Proteins which are secreted by tumor cells, for example MMP-2 and -9, can destroy the ECM and facilitate tumor cell invasion and metastasis." (PMID 24527098, 2014). "The WISP-1 gene encodes the Wnt-induced secreted protein-1, which has been shown to enhance tumor cell migration by increasing MMP-2 expression, and to inhibit anti-tumor immunity by blocking the response of immune cells to IL-12." (PMID 24887580, 2014). "A number of studies revealed positive correlations between tumor invasion and the activities of the gelatinases MMP-2 and MMP-9." (PMID 25097794, 2014). "They developed a simple MMP-2-sensitive self-assembling copolymer, PEG-pp-PEI-PE using a synthetic octapeptide (GPLGIAGQ) which was also utilized in their previous investigations with both, liposomes and micelles for MMP-2-sensitive tumor targeting." (PMID 24795633, 2014). "Second, inhibition of the ICMT-Rac1 signaling by miR-100 attenuated lamellipodia formation and MMP2 activation, which are the essential events for the migratory and invasive activity of tumor cells." (PMID 25361001, 2014). "Following the administration of α-solanine (6 μg/g for 2 weeks) in xenograft model, tumor volume and weight were decreased by 61% and 43% (p<0.05) respectively, showing decreased MMP-2/9, PCNA and VEGF expression." (PMID 24505326, 2014). "Most important, in situ zymography with an MMP-2 inhibitor for the first time demonstrated a strong impact of MMP-9 activity on the degree of tumor infiltration during PTC progression." (PMID 24778099, 2014). "Matrix metalloproteinase-2 (MMP-2) is capable of degrading the majority of components of the extracellular matrix and is regarded to closely correlate with tumor invasion and metastasis." (PMID 25013467, 2014). "MMP2 has a dual role in tumor infiltration, transfer and angiogenesis, which helps to determine patients’ sensitivity during traditional treatment, and has inspired efforts to develop bio-specific therapy for tumors." (PMID 25347277, 2014). "MMP2 and MMP9 have been particularly associated with tumor progression, metastatic dissemination, and poor survival in different human cancers, including ccRCC." (PMID 24931473, 2014). "Immunohistochemistry of HCC tissues revealed the location of CD147 on cell membrane within tumor compartment and MMP-2 expression in both tumoral and stromal compartments." (PMID 24996644, 2014). "At the post-translational level, MT1-MMP specifically activates the latent pro-MMP-2 on the tumor cell surface through the formation of a complex with TIMP-2." (PMID 24978435, 2014). "Immunohistochemical analyses revealed that MMP-9, MMP-2, and uPA expression levels were markedly reduced after all treatments in both in vivo tumor models." (PMID 24900952, 2014).
tumor (continued). "MMP-2 is secreted as a proenzyme (proMMP-2) and located on the cell surface of tumor cells and requires activation to exert its catalytic activation." (PMID 24511528, 2014). "We focused on development of a metastatic tumor imaging techniques using nanoparticles that specifically target MMP-2 in cancer cells." (PMID 25547485, 2014). "While TLX occupies the MMP-2 promoter endogenously, Oct-4 occupancy occurs in a hypoxic milieu, under which conditions these tumor cells would acquire a more epigenetic and phenotypic resemblance to stem cells." (PMID 25356871, 2014). "We also found that Dp44mT can antagonize the tumor invasion and by abrogating the induction of gelatinase activity (MMP2)." (PMID 25261367, 2014). "Since MMP-2 can be released from malignant cells or surrounding stromal components, the relative contribution of MMP-2 secretion from each compartment to tumor progression has been studied." (PMID 24978435, 2014). "It is generated through proteolytic cleavage of circulating plasminogen by a series of enzymes from the tumor environment, including the MMPssuch as MMP-2, MMP-7, MMP-9, and MMP-12." (PMID 25549350, 2014). "In vitro and in vivo, we proved that PDGF-D significantly promoted tumor growth and invasion through up-regulating MMP2 and MMP9, and inducing EMT." (PMID 24646915, 2014). "Because collagen IV is one of the major components of the basement membrane, MMP-2, a 72 kDa type IV collagenase, is believed to be of special significance during tumor invasion." (PMID 24511528, 2014). "Matrix metalloproteinase-2 (MMP-2) is an endopeptidase that facilitates extracellular matrix remodeling and molecular regulation, and is implicated in tumor metastasis." (PMID 25317077, 2014). "Immunohistochemical analysis on the subcutaneous tumor tissues also confirmed that MMP-2 was decreased upon ATF3 expression." (PMID 25149542, 2014). "In the control group, MMP-2-positive cells were extensively observed within the primary tumor, and the MMP-2-labeling index was 48 ± 2% (n = 8)." (PMID 24690154, 2014). "CD147/EMMPRIN is known to induce MMP production, such as MMP2, to promote tumor growth, inhibit cell apoptosis and enhance cell migration under hypoxic conditions." (PMID 25269858, 2014). "Although plasmin has been shown to principally activate MMP-1, -3 and -9, increasing evidence proves that uPA/plasmin can activate pro-MMP-2 and thereby promoting tumour invasion and metastasis 53,54." (PMID 25215932, 2014). "MMP-2 level in tumor loci was scored and showed a positive correlation with the concentration of soluble CD147 in serum (r = 0.650, P = 0.009)." (PMID 24996644, 2014). "MMP-2 is also produced by bone marrow-derived MSCs recruited to the tumor site in response to OCCs secretion of LL-37." (PMID 25303976, 2014). "Although various MMPs have been implicated in acquisition of invasive and metastatic properties by tumor cells, MMP-2 and MMP-9, which degrade type IV collagen, a major component of basement membranes, are majorly associated with metastasis." (PMID 25296976, 2014). "MMP-2 was expressed not only in the cytoplasm of tumor cells but also in the cytoplasm of prostatic stromal cells, endothelium, fibroblasts, smooth muscle cells, macrophages, and lymphocytes." (PMID 25097794, 2014). "The tumor secretion of stem cell factor functions as a chemoattracting signal for mast cells; then mast cells produce angiogenic factors and MMPs (MMP-2 and MMP-9) to promote tumor vascularization." (PMID 24578639, 2014). "The authors suggested that active MMP-2 is recruited to the leading edge of invasive tumor cells and cleaves fibronectin into shorter fibronectin products." (PMID 25050916, 2014). "Ectopic expression of miR-874 suppressed tumor migration and invasion and down regulated MMP-2, -9 and -14." (PMID 24670365, 2014). "MDAP3000 pretreated with MMP-2 showed higher accumulation in tumor cells, and was completely blocked by additional treatment with an MMP inhibitor." (PMID 25010662, 2014).
tumor (continued). "Serum Ang-2 and MMP-2 and tumor HIF-1α were identified as relevant baseline biomarkers of sunitinib activity in advanced RCC, warranting further research into their prognostic versus predictive value." (PMID 25100134, 2014). "Expression of MMP-2 in tumor cells was significantly higher at the positive margins than in the main tumor mass (P = 0.0301)." (PMID 25097794, 2014). "The tumor suppressor RECK is able to suppress tumor angiogenesis, invasion and metastasis, inhibiting MMP-2 and MMP-9." (PMID 25909813, 2014). "cDNA microarray demonstrated that the expression of MMP-2 and -9 were suppressed in fat-1 mice-derived TC-1 tumor while those of other MMPs were tended to be upregulated when compared to controls." (PMID 24586907, 2014). "Recently, MMP2 was identified as a key factor of the vicious cycle of osteoblasts and metastatic tumor cells." (PMID 24292404, 2014). "Most important, in situ zimography with an MMP-2 inhibitor for the first time demonstrated a strong impact of MMP-9 activity on the degree of tumor infiltration during PTC progression." (PMID 24778099, 2014). "A great many studies have proved the vital roles of Hsp90a and MMP-2 in tumor invasion and progression; hence, it is reasonable to presume the prooncogenic function in cancer." (PMID 25580113, 2014). "MMP2 is not only of great significance in tumor infiltration and transfer, but also plays a role in tumor angiogenesis." (PMID 25347277, 2014). "Following this MDAP strategy, the probe was expected to be cleaved by MMP-2 enzymatic activity in the vicinity of the tumor, and efficiently trapped in proximal tumor cells." (PMID 25010662, 2014). "In our pilot study, we detected the expression of 4 proteins which were closely related with the invasive potential of tumor cells, including vimentin, RhoA, RhoC and MMP-2." (PMID 24658581, 2014). "We detected a significant difference in MMP-2 expression on the positive margin versus that in the main tumor mass (P = 0.0301)." (PMID 25097794, 2014). "It turns out that MMPs play a crucial role in the tumor growth, invasion, metastasis, and angiogenesis in cancer tissue, in which gelatinase (MMP-2, MMP-9) is closely related to malignant tumors." (PMID 24971318, 2014). "PMNs activate matrix metalloproteinase-2 (MMP-2), an enzyme involved in angiogenesis, tentatively stimulating tumour progression and invasion." (PMID 24694107, 2014). "MMP-2 and MMP-9, activated by plasmin, are markers associated with the tumor invasion and metastasis." (PMID 25222667, 2014). "In the genistein/metastasis(-) subgroup, the primary tumor contained fewer MMP-2-positive cells compared with the control group, and the MMP-2-labeling index [20 ± 5% (n = 6)] was lower (p < 0.01) than that of the control group." (PMID 24690154, 2014). "More impressively, the images clearly show the diffusion of the tumor-targeted MMP2/LHRH Mn3O4 NPs from site of administration to the tumor and preferential accumulation in the primary tumor and metastases." (PMID 24919932, 2014). "In this study, the levels of MMP-2 expression positively correlated with tumor progression and worse survival." (PMID 25667918, 2014). "Gene expression analysis revealed a reduction in expression of the proteases Cathepsin D and MMP-2 in the OPG knockdown cells with reduced levels of MMP-2 maintained after primary tumor growth." (PMID 24976340, 2014). "Although plasmin has been shown to principally activate MMP-1, -3, and -9, increasing evidence proves that uPA/plasmin can activate pro-MMP-2 and thereby promoting tumor invasion and metastasis." (PMID 25170871, 2014). "MMP-2 and -9 can cleave latency-associated peptide to activate tissue growth factor β1, MMP-2 and MMP-9 have been shown to be critical for the “angiogenic switch in tumor angiogenesis." (PMID 25233229, 2014).